CFL2 (cofilin 2)
Description:
Controls reversibly actin polymerization and depolymerization in a pH-sensitive manner. Its F-actin depolymerization activity is regulated by association with CSPR3. It has the ability to bind G- and F-actin in a 1:1 ratio of cofilin to actin. It is the major component of intranuclear and cytoplasmic actin rods. Required for muscle maintenance. May play a role during the exchange of alpha-actin forms during the early postnatal remodeling of the sarcomere (By similarity).
Synonyms: NEM7
Tractability: Antibody: the Human Protein Atlas places it where antibodies can reach. PROTAC: ubiquitination databases record sites on it; its protein half-life has been measured.
Gene: Protein-coding gene on chromosome 14 (34,709,113 to 34,714,823, reverse strand). Ensembl gene ENSG00000165410.
Subcellular location: Nucleus matrix; Cytoplasm, cytoskeleton
Subcellular location (Human Protein Atlas): Plasma membrane; Cytosol; Nucleoplasm
Gene Ontology:
Molecular function: protein binding; actin filament binding; actin binding
Biological process: actin filament depolymerization; positive regulation of actin filament depolymerization; actin filament fragmentation; actin filament severing; actin polymerization or depolymerization
Cellular component: extracellular exosome; extracellular region; I band; Z disc; cytoplasm; actin cytoskeleton; cytoskeleton; nuclear matrix
Genetic constraint (gnomAD): Loss-of-function variants: 7 observed, 14.45 expected, observed/expected ratio (o/e) 0.48, 90% interval 0.27 to 0.91. The upper end of that interval is the gene's LOEUF score, 0.91, which puts it in group 3 of 6, group 1 being the genes least tolerant of losing a copy. Missense variants: 101 observed, 145.29 expected, observed/expected ratio (o/e) 0.7, 90% interval 0.59 to 0.82. Synonymous variants: 45 observed, 52.18 expected, observed/expected ratio (o/e) 0.86, 90% interval 0.68 to 1.11.
Gene-disease validity (ClinGen):
ClinGen rates the evidence that CFL2 causes each of these diseases.
nemaline myopathy 7 (autosomal recessive): Definitive. Any nemaline myopathy in which the cause of the disease is a mutation in the CFL2 gene.
Homologues: Orthologues: chimpanzee CFL2 (100% identical), guinea pig CFL2 (100% identical), macaque CFL2 (100% identical), pig CFL2 (100% identical), dog CFL2 (99% identical), mouse Cfl2 (99% identical), rabbit CFL2 (99% identical), rat Cfl2 (99% identical), zebrafish cfl2 (89% identical), tropical clawed frog cfl2 (88% identical), Drosophila melanogaster tsr (30% identical), Caenorhabditis elegans F53E2.2 (26% identical), and 2 more. Paralogues in human: CFL1 (81% identical), DSTN (69% identical).
Diseases named in the same sentence as CFL2 in open-access papers:
CFL2 is named in the same sentence as 49 diseases in open-access papers, as found by Europe PMC text mining. Sharing a sentence is not in itself a finding about the gene and the disease. The quoted sentences say what the papers report.
nemaline myopathy (9 papers, 2010 to 2025). Nemaline myopathy (NM) encompasses a large spectrum of myopathies characterized by hypotonia, weakness and depressed or absent deep tendon reflexes, with pathologic evidence of nemaline bodies (rods) on muscle biopsy. "In humans, missense mutations in CFL2 are associated with nemaline myopathy and myofibrillar myopathy, with loss of cofilin-2 functions resulting in sarcomeric and cytoskeletal disorders." (PMID 38003645, 2023). "Mutations in cofilin 2 (CFL2), coding for the actin-binding protein cofilin-2, were identified in patients with nemaline myopathy with minicores and concentric laminated bodies." (PMID 35980353, 2022). "Similarly, mutated cofilin-2 has been previously shown to cause nemaline myopathy." (PMID 34433058, 2021). "Mutations in ten different genes cause nemaline myopathy: skeletal muscle α-actin (ACTA1), nebulin (NEB), α-tropomyosin, β-tropomyosin, troponin T1, cofilin 2 (CFL2), KBTBD13, KLHL40, KLHL41 and leiomodin 3 (LMOD3)." (PMID 25931053, 2015). "Other causative genes in CRM have been reported (CFL2, ACTA1, and TPM3), although some of them are typically associated with nemaline myopathy, where cores are not present." (PMID 35980353, 2022). "A prime example is nemaline myopathy (NM), the most common non-dystrophic congenital skeletal muscle myopathy that is caused by mutations in six genes that all encode thin filament proteins (TMP2, TMP3, NEB, ACTA1, TNNT1, CFL2)." (PMID 23437068, 2013).
breast carcinoma (8 papers, 2013 to 2023). "To further elucidate the specific role of miR-200c in regulating breast cancer cell migration through CFL2 regulation, we co-transfected a miR-200c mimic with a plasmid encoded with CFL2 cDNA in MDA-MB-231 cells." (PMID 23497265, 2013). "The same result was observed in breast cancer tumor tissue, where CFL2 expression increased with tumor grade." (PMID 38001634, 2023). "In breast cancer, upregulation of CFL2 was detected in aggressive cell lines and tissues; similar findings were also observed in prostate cancer, promoting proliferation and migration in cell lines." (PMID 38001634, 2023). "Tissue microarray analysis showed that CFL2 expression in breast cancer tissue was positively correlated with tumor grade." (PMID 29342841, 2018). "In the GSE40059 breast cancer study, the authors investigated differences between aggressive breast cancer cell lines and less-aggressive cell lines and reported that CFL2 was up-regulated by miR-200c." (PMID 28362846, 2017). "Cfl-2 has been overexpressed in aggressive breast cancer cell lines, and its expression has been correlated with tumor grade in primary breast cancer tissue." (PMID 28025492, 2016). "In order to further investigate the functional role of cofilin-2 in the migration and invasion of breast cancer cells, the MDA-MB-231 cells were transiently transfected with a CFL2-specific siRNA." (PMID 23497265, 2013). "Tissue microarray analysis further revealed that CFL2 expression in primary breast cancer tissue correlated with tumor grade." (PMID 23497265, 2013). "Tissue microarray analysis (TMA) further demonstrated that CFL2 expression in primary breast cancer tissue was positively correlated with tumor grades." (PMID 23497265, 2013). "We characterized one of the target genes of miR-200c, CFL2, and demonstrated that CFL2 is overexpressed in aggressive breast cancer cell lines and can be significantly down-regulated by exogenous miR-200c." (PMID 23497265, 2013). "Likewise, cofilin-2 is an important regulator of actin dynamics, and has been shown to be overexpressed in agressive forms of breast cancer." (PMID 26657485, 2015). "We experimentally validated the predicted miR-142-3p targets ROCK2, CFL2, RAC1, WASL, and ITGAV in St-T1b cells using qPCR, which is in accordance with our previous findings in breast cancer cells." (PMID 32824678, 2020).
congenital myopathies (8 papers, 2015 to 2025). "Mutations in CFL2 gene mutations have been associated with congenital myopathies, including nemaline and myofibrillar myopathy." (PMID 36552740, 2022). "Mice with mutations in Grin1 also show abnormal anxiety-like behaviors, a deficiency in fear memory, and a decreased startle amplitude, and mice with Cfl2 mutations display features of congenital myopathy." (PMID 28751711, 2017). "Mutations in the gene for cofilin-2 (CFL2) have been identified in several families as a cause of congenital myopathy with nemaline bodies and cores." (PMID 25874796, 2015). "The role of CFL2 has been studied in cardiac muscle and many types of congenital myopathies, but not in chicken skeletal muscle development." (PMID 34276416, 2021).
prostate carcinoma (6 papers, 2017 to 2024). A carcinoma that arises from epithelial cells of the prostate gland. "For example, SOX2-OT accelerates cell proliferation and migration in prostate cancer by targeting the miR-369-3p/CFL2 axis." (PMID 34394184, 2021). "Overexpression of CFL2 exacerbated the carcinogenic behavior of prostate cancer cells." (PMID 34903141, 2021). "Moreover, CFL2 acts as a target gene of miR-369-3p in prostate cancer." (PMID 34903141, 2021). "The percentages of alterations in these genes among prostate cancer varied from 13-30% for individual genes (CAP2, 19%; CAP1, 13%; CFL1, 30%; CFL2, 21%; DSTN, 19%); the CFL1 gene was amplified predominantly in the prostate cancer type." (PMID 28423713, 2017). "For example, percentages of alterations in CAP2, CAP1, CFL1, CFL2, DSTN, ACTB, and ACTG1 genes among prostate cancer varied from 2.6–30% in individual genes (CAP2, 19%; CAP1, 13%; CFL1, 30%; CFL2, 21%; DSTN, 19%; ACTG1, 2.6%; ACTB, 21%;); the CFL1 gene was amplified predominantly in prostate cancer." (PMID 28423713, 2017).
Alzheimer disease (3 papers, 2019 to 2024). A progressive, neurodegenerative disease characterized by loss of function and death of nerve cells in several areas of the brain leading to loss of cognitive function such as memory and language. "The isoform Cofilin 2 increases in the serum of Alzheimer’s disease patients, and it has been suggested as a highly sensitive and specific diagnostic biomarker." (PMID 38999977, 2024).
Obesity (3 papers, 2021 to 2022). Accumulation of substantial excess body fat. "The roles of miR-325-3p on CFL2 expression and myogenic differentiation suggest a novel miRNA-mediated mechanism that regulates myogenesis in the background of obesity." (PMID 34685705, 2021). "Our study highlights the importance of miR-429-3p targeting CFL2 during myoblast differentiation and suggests a putative miRNA-mediated regulatory mechanism for myogenesis in the background of obesity." (PMID 34681631, 2021). "Here, we unveiled an essential role of miR-325-3p on CFL2 expression, myoblast proliferation, and myogenic differentiation, which contributes to our current understanding of the miRNA-mediated myogenic regulatory mechanism in the background of obesity." (PMID 34685705, 2021). "The roles of miR-325-3p on CFL2 expression, F-actin modulation, and myogenic differentiation suggest a novel miRNA-mediated regulatory mechanism of myogenesis and PA-inducible miR-325-3p may be a critical mediator between obesity and muscle wasting." (PMID 34685705, 2021). "In conclusion, our current study highlights the role of miR-320-3p on CFL2 expression, YAP1 activation, and myoblast differentiation and suggests that PA-inducible miR-320-3p is a significant mediator of muscle wasting in obesity." (PMID 35054986, 2022).
pancreatic cancer (3 papers, 2014 to 2023). "Cofilin-1 involved in motility and invasion is up-regulated in pancreatic carcinoma tissues while muscle cofilin-2 was reported to be downregulated." (PMID 25188245, 2014). "In contrast, in pancreatic cancer, CFL2 showed lower expression compared with non-cancerous tissues." (PMID 29342841, 2018). "However, our results indicate that compared to adjacent nontumor samples, CFL2 is downregulated at both the mRNA and protein levels in IGC patient tumors, similar to what was observed in pancreatic cancer." (PMID 38001634, 2023).
atherosclerosis (2 papers, 2024 to 2025). A disease characterized by the build-up of fatty material and calcium deposition in the arterial wall resulting in partial or complete occlusion of the arterial lumen. "A decrease in CFL2 expression may impact the morphology and function of vascular smooth muscle cells, thereby influencing the development of atherosclerosis." (PMID 38660678, 2024).
dilated cardiomyopathy (2 papers, 2017 to 2020). Cardiomyopathy which is characterized by dilation and contractile dysfunction of the left and right ventricles. "Importantly, we demonstrate that the P20L Hsp20 mutation associated with dilated cardiomyopathy exhibits reduced physical interaction with 14-3-3 due to diminished Ser16 phosphorylation, with subsequent failure to translocate to the cytoskeleton and inability to disassemble the 14-3-3/CFL2 complex." (PMID 33339131, 2020). "Our findings provide an additional and important layer of Cfl2 regulation, which we believe has an extended role in cardiac signal transduction and dilated cardiomyopathy presumably due to the reported involvement of Cfl2 in these mechanisms." (PMID 28886070, 2017).
gastric cancer (2 papers, 2018 to 2023). A primary or metastatic malignant neoplasm involving the stomach. "Data mining based on Kaplan–Meier plots showed that high CFL2 expression is associated with poor overall survival and first progression in gastric cancer." (PMID 29342841, 2018). "Overexpression of CFL2 reversed the reduced cell proliferation and migration induced by the transfection of miR-3189-3p mimics, suggesting that miR-3189-3p suppressed the proliferation and migration of gastric cancer cells by directly inhibiting CFL2 expression." (PMID 29342841, 2018). "Data from gastric cancer cells SGC7901 and BGC823 transfected with miRNA-194 (upregulated in our study targeting CFL2) identified downregulated CFL2 as one of the top 23 coding genes most downregulated by miR-194 mimics in GC." (PMID 38001634, 2023). "Additionally, by data mining in the Kaplan–Meier plotter, we found that high CFL2 expression was associated with poor OS (overall survival) and FP (first progression) in patients with GC, suggesting that CFL2 was an unfavorable prognostic factor for gastric cancer." (PMID 29342841, 2018).
idiopathic dilated cardiomyopathy (2 papers, 2019 to 2024). Decreased function of the heart associated with cardiac enlargement and congestive heart failure, of unknown cause. "Cofilin-2, an actin protein involved in aggregation, has specifically been implicated in cytoplasmic aggregates found in both AD brains and the myocardium of idiopathic dilated cardiomyopathy." (PMID 39766777, 2024). "Cofilin 2 was previously reported to be significantly increased in protein expressions and phosphorylation levels, which was participated in the pathogenesis of idiopathic dilated cardiomyopathy with amyloid-like aggregates." (PMID 31447667, 2019).
arteriosclerosis (1 paper, 2025). A vascular disorder characterized by thickening and hardening of the walls of the arteries. "The outcomes of the IVW analysis indicated that CFL2 (OR = 0.901, 95% confidence interval [CI]: 0.817–0.993, P = .036) was associated with PAS, with PIP5K1B (OR = 0.740, 95% CI: 0.570–0.961, P = .024) identified as a protective factor against arteriosclerosis." (PMID 40419934, 2025).
bladder cancer (1 paper, 2022). "According to previous studies, the CFL2 gene is a tumor suppressor gene in the oncogene sequence of bladder cancer, which has the biological significance of “Axon guidance”, “FC gamma R‐mediated”,28 and actin cytoskeleton regulation." (PMID 34541834, 2022).
breast tumor (1 paper, 2013). "To determine if CFL2 is associated with breast tumor progression, we performed TMA analysis on 205 primary breast tumor and 5 normal breast tissue samples." (PMID 23497265, 2013).
cognitive decline (1 paper, 2019). "A significant correlation between cofilin 2 levels and cognitive decline was observed (r = –0.792; p < 0.001)." (PMID 31447667, 2019). "The correlation analysis between cofilin 2 levels and cognitive decline was also performed to determine whether higher cofilin 2 expression was associated with more severe disease or not." (PMID 31447667, 2019).
colon cancer (1 paper, 2018). "Moreover, we noted that some of the mRNAs (ANLN, CFL2, FJX1, HHIP, PANX2, SCN3A, VSNL1 and ZIC2) were also associated with overall survival in patients with colon cancer." (PMID 29420609, 2018).
dementia (1 paper, 2019). Loss of intellectual abilities interfering with an individual's social and occupational functions. "Additionally, to test whether cofilin 2 could distinguish AD from another common dementia-vascular dementia (VaD), we measured cofilin 2 serum levels in VaD, compared the expressions between AD and VaD, and also performed the relevant ROC analysis." (PMID 31447667, 2019).
diabetic cardiomyopathy (1 paper, 2024). Diabetic cardiomyopathy is a disorder of the heart muscle in people with diabetes. "LncRNA TUG1 exacerbates MF in diabetic cardiomyopathy by modulating the miR-145a-5p/cofilin-2 (Cfl2) axis." (PMID 38476331, 2024).
diabetic retinopathy (1 paper, 2023). "Circ-PSEN1, also known as circ_0008521, regulates ferroptosis in retinal pigment epithelial cells of patients with diabetic retinopathy (DR) via the miR-200b-3p/cofilin-2 (CFL2) axis." (PMID 37332354, 2023).
endometrial adenocarcinoma (1 paper, 2022). "After MDGA1 was removed, the remaining candidate hub genes (RECK, CFL2, TGFBR3, TPM2, and C10ORF91) affecting the survival rate of endometrial adenocarcinoma in the MEbrown module and MEturquoise module were selected." (PMID 35123404, 2022).
glioblastoma multiforme (1 paper, 2018). "The overexpression of CFL2 gene in glioblastoma multiforme contributes to increased therapeutic response." (PMID 29342841, 2018).
head-neck cancer (1 paper, 2017). "Co-expression analysis revealed that CAP1 was coexpressed with TUBA1B both in pancreatic and head-neck cancer, as well as with CFL1, CFL2, DSTN, and ROBO1, according to STRING analysis." (PMID 28423713, 2017). "The co-expression analysis revealed that CAP1 was coexpressed with TUBA1B in pancreatic and head-neck cancer, as well as with CFL1, CFL2, DSTN, ACTB, ACTG1, and ROBO1, according to the STRING analysis." (PMID 28423713, 2017).
invasive breast carcinoma (1 paper, 2013). A carcinoma that infiltrates the breast parenchyma. "Finally, we characterized one of the target genes of miR-200c, CFL2, and demonstrated that CFL2 is overexpressed in invasive breast cancer cell lines and regulated by miR-200c." (PMID 23497265, 2013).
liver cancer (1 paper, 2017). An epithelial or non-epithelial malignant neoplasm that arises from the liver. "CAP2 was coexpressed with TP53BP2, ENA/VASP in the liver cancer, and CFL1, CFL2, DSTN, ACTB, ACTG1, and ROBO1." (PMID 28423713, 2017).
mild cognitive impairment (1 paper, 2019). "The serum levels of cofilin 2 in AD or mild cognitive impairment (MCI) patients were significantly higher compared to controls (AD: 167.9 ± 35.3 pg/mL; MCI: 115.9 ± 15.4 pg/mL; Control: 90.5 ± 27.1 pg/mL; p < 0.01)." (PMID 31447667, 2019).
myocardial hypertrophy (1 paper, 2022). "The levels of phosphorylated cofilin-2 are increased in myocardial hypertrophy through the activation of LIM-kinase (LIMK) by ROCK, which is induced by multiple neurohumoral factors, such as angiotensin II, endothelin 1 and leptin." (PMID 36428995, 2022). "The abundance change in cofilin-2 does not play a role in the morphogenesis of neonatal rat cardiomyocytes, while its activity is closely associated with the development of cardiac hypertrophy." (PMID 36428995, 2022).
oral candidiasis (1 paper, 2010). Infection of the mucosal lining of the mouth with the fungus Candida albicans. "The gene coding for Rim101 and three (in)direct target genes (FTH1, FRE4 (orf19.1844), CFL2,) proposed by the model were also up-regulated within expression data of patients suffering from oral candidiasis." (PMID 21050438, 2010).
Stroke (1 paper, 2025). Sudden impairment of blood flow to a part of the brain due to occlusion or rupture of an artery to the brain. "Nine days post-stroke, proteins annotated as thin filaments were upregulated, including Ablim1, Dbnl, Parvb, Capg, and Pdlim3; Actn2, Pdlim7, Tpm1, and cofilin 2 (Cfl2) were downregulated." (PMID 41226396, 2025).
tongue tumor (1 paper, 2018). "The present study identified cofilins (CFL1 and CFL2) and tropomyosin family proteins (TPM3 and TPM4) are significantly upregulated, in contrast, myosin family proteins (MYL2, MYL4 and MYLPF) were downregulated in tongue tumor samples as compared to normal samples." (PMID 29371635, 2018).
vascular dementia (1 paper, 2019). A degenerative vascular disorder affecting the brain. "In addition, the expression of cofilin 2 was found to be significantly increased in AD compared to vascular dementia (VaD), and only an increased trend but not significant was detected in VaD compared to the controls." (PMID 31447667, 2019).